IL6 (interleukin 6)
Diseases named in the same sentence as IL6 in open-access papers (continued):
Sharing a sentence is not in itself a finding about the gene and the disease.
periodontal disease (continued). "Moreover, it was confirmed that the severity of the periodontal disease and the serum levels TNF-α, IL-6 and CRP were significantly correlated." (PMID 26644840, 2015). "Our findings showing that kakkonto decreases LPS-induced PGE2 production suggest that kakkonto also has anti-inflammatory effects in periodontal disease and that its effects are mainly mediated by suppression of PGE2 production even though kakkonto increased LPS-induced IL-6 and IL-8 production." (PMID 24693448, 2014). "IL-6 systemic and GCF levels increase in destructive periodontal diseases." (PMID 24068858, 2013). "Numerous studies show that patients with periodontal disease have elevated levels of systemic inflammatory mediators compared to healthy controls, including C-reactive protein (CRP), interleukin 1 (IL-1), interleukin 6 (IL-6), and tumor necrosis factor-α (TNF-α)." (PMID 40026941, 2025). "The presence of chronic inflammation, as seen in periodontal disease, for example, may increase IL-6 amplifier activation, and older adults without dental visits may be more prone to IL-6 amplifier activation due to periodontal disease." (PMID 39767507, 2024). "This correlation may be attributed to inflammatory and immunological responses common to both periodontal disease and systemic diseases, leading to an increase in circulating inflammatory cytokines, such as C-reactive protein (CRP), interleukin (IL)-6, and tumor necrosis factor (TNF)-α." (PMID 38132221, 2023). "The authors concluded, it is likely that elevated IL-6 reflects the degree of subclinical inflammation in periodontal tissues, which can be a link between periodontal disease and OSAS, and the presence or severity of OSAS does not affect the level of IL-1β and IL-21 in either plasma or saliva." (PMID 26998377, 2016). "Inflammatory mediators includinginterleukin-1 beta (IL-1β), IL-6, tumor necrosis factor alpha (TNF-α) and beta-glucuronidase (β–glucuronidase) were tested and analyzed among women with overall periodontal disease (n = 442) or moderate/severe periodontal disease (n = 247)." (PMID 27978823, 2016). "However, when either serum IL-6 or CRP was added to the model, severe periodontal disease was no longer significantly associated." (PMID 23950871, 2013). "The biological mechanisms that may drive the relationships between periodontal diseases and poor pregnancy and infant outcomes include but are not limited to the systemic dissemination of inflammatory cytokines like IL-1, IL-6, PGE2, and TNF-β that can be up-regulated by bacterial by-products." (PMID 39540631, 2024). "Salivary levels of IL-6 and IL-33, which regulate cell recruitment amid the transition from acute to chronic inflammation, have been observed to increase in patients contending with obstructive sleep apnea, independent of the severity of their periodontal disease." (PMID 38093226, 2023). "Moreover, according to recent systematic reviews and meta-analyses, salivary IL-1β, IL-6, and MMP-8 are among the five promising biomarkers that have been identified as eligible candidates for the diagnosis of periodontal diseases; while IL-10 may have a strong regulatory effect on immune responses." (PMID 35368315, 2022). "The value of monitoring GCF IL-6 and IL-8 was not evident in our study; further studies are required to clarify the exact role of these cytokines in periodontal disease and to evaluate other factors that in conjunction with local ones may influence their levels in GCF." (PMID 22114600, 2012). "In fact, the levels of IL-6 and PGE2 in amniotic fluid have been reported to be higher in pregnant women with periodontal disease during pregnancy than in those without periodontal disease during pregnancy." (PMID 36163018, 2022). "In support, inflammatory cytokines IL-6, IL-17A, and IL-33 were increased in the saliva of SLE/periodontal disease patients compared to non-SLE subjects with periodontal disease." (PMID 34950607, 2021).
periodontal disease (continued). "According to our results, IL-6 and TNF-α salivary levels appears to have potential to distinguish pregnant women with and without periodontal disease." (PMID 29740515, 2018). "Moreover, it is possible that the expression of IL-6 and IL-10 can alter the levels of other cytokines or inflammatory factors that play a significant role only in the initiation of the inflammatory response and not in the healing process after treatment of periodontal disease." (PMID 28624837, 2017). "Further clinical trials could focus on immunological markers like aMMP-8, sIL-6R, calprotectin, IL-6, TNF-α, IL-1 in people without advanced periodontal disease and periodontally severe diseased people to finally clarify the evidence." (PMID 39786483, 2025). "While no prior studies have specifically investigated CTRP-1 in periodontal disease, its role as a modulator of inflammation- through its influence on pro-inflammatory molecules such as TNF-α and IL-6- has been well established in other inflammatory conditions." (PMID 40542868, 2025). "Significantly increased concentrations of inflammatory mediators of IL-1β, IL-6, TNF-α and β-glucuronidase in saliva and IL-1β, β-glucuronidase and TNF-α in serum were found among pre-conception women with moderate/severe periodontal disease, compared with women without periodontal disease." (PMID 27978823, 2016). "In addition, periodontal disease patients with CKD indicators had a higher percentage of high of CRP (≥1.03 mg/L), high TNF-α (≥1.12 ng/L) and high IL-6 (≥7.54 ng/L) levels than those without indictors of kidney damage." (PMID 23951003, 2013).
Autoimmunity (337 papers, 2008 to 2026). The occurrence of an immune reaction against the organism's own cells or tissues. "Increased AST and IL-6 levels are indicative of an inflammatory response, which are associated with several inflammatory and autoimmune conditions." (PMID 40110047, 2025). "Tripartite motif containing-21 (TRIM21) and interleukin-6 (IL-6) have been implicated in autoimmunity and inflammation, with links to chronic interferon activity." (PMID 41050477, 2025). "Chronic increases of IL-6 have been linked to autoimmune conditions and have been functional as a target for the treatment of RA with tocilizumab, an anti-IL-6 receptor antibody." (PMID 39968418, 2025). "HFD diet causes the production of proinflammatory cytokines, IL-6, IL-1β, and Th17, which causes gut inflammation and CNS autoimmunity, finally leading to MS." (PMID 41008984, 2025). "In the context of inflammation, infectious disease, or autoimmunity, IL-6 signaling is a key stimulus for innate immune responses and, when dysregulated, is implicated in the pathogenesis of autoimmune disorders." (PMID 38689325, 2024). "In PsO, IL-6 contributes directly to the differentiation of pathogenic Th17 cells, which are associated with the initiation of autoimmunity and inflammation." (PMID 38025060, 2023). "The dysregulation of IL-6 signalling is particularly implicated in the pathogenesis of numerous inflammatory pathologies, ranging from chronic inflammatory diseases to autoimmune disorders." (PMID 38025060, 2023). "Cblb is a Cbl family E3 ubiquitin ligase that restrains pathogenic Th17 cells generation and Th17-related autoimmunity by suppressing macrophages’ IL-6 secretion." (PMID 37894114, 2023). "IL-6 has been reported to promote the development of spontaneous germinal centers in secondary lymphoid tissues, associated with autoimmunity and autoinflammation." (PMID 37512494, 2023). "This has been attributed to the idea that the immune system tightly regulates Th17/Treg cell homeostasis through the IL-6 axis, and the disturbance of this balance causes autoimmunity." (PMID 37762312, 2023). "Multiple studies investigating the PMN have implicated interleukin 6 (IL-6), a pro-inflammatory cytokine known to have pathologic effects in the dysregulated processes of chronic inflammation and autoimmunity." (PMID 35954395, 2022). "Induction with IL-1β, IL-6, and IL-23 is associated with chronic inflammation, enhanced autoimmunity, and anti-tumor immunity." (PMID 36248881, 2022). "IL-6 production and dysregulation are associated with chronic inflammatory diseases and autoimmunity." (PMID 35958622, 2022). "The pro-inflammatory cytokine interleukin-6 (IL-6) is another example of a therapeutic target that has been linked to both autoimmunity and cancer." (PMID 36275816, 2022). "In particular, we noted a robust increase in IL-6, an inflammatory cytokine linked to autoimmunity and inflammation in mice and humans." (PMID 35653193, 2022). "Basic research identified interleukin-6 (IL-6) as a cytokine with pleotropic activities and underlying abilities to promote inflammation and autoimmunity." (PMID 36260501, 2022). "IL-6 is a crucial cytokine in CNS autoimmunity establishment, as IL-6-deficient mice have shown attenuated EAE symptoms." (PMID 34489926, 2021). "Deregulation of IL-6 signalling has been associated with chronic inflammation, autoimmunity, infectious diseases and cancer, where it often acts as a diagnostic or prognostic indicator of disease activity and response to therapy." (PMID 34361105, 2021). "The expression of receptor 3 of S1P was associated with the development of autoimmunity as well as the increased downstream signaling and the production of cytokine IL-6." (PMID 32349258, 2020). "Normally, IL-6 is strictly regulated by transcriptional and posttranscriptional mechanisms and is implicated in inflammation and autoimmunity." (PMID 30642099, 2019).
Autoimmunity (continued). "Pro-inflammatory cytokines, such as TNF-α and IL-6, have been shown to pose a multitude of biological effects linked to autoimmunity, and acute or chronic inflammatory diseases." (PMID 30486383, 2018). "IL-6 has also been linked to pro-inflammatory and Th17 immune responses, which are related to autoimmunity and closely related to risks for NHL." (PMID 30873511, 2018). "For example, IFN-γ contributes to the pathogenesis of autoimmunity and IL-6 is associated with joint damage in RA." (PMID 27143816, 2016). "Collectively, these results increase the evidence that IL-6 plays a central role in the pathogenesis of T cell-mediated autoimmunity, but the underlying mechanisms remain incompletely understood." (PMID 24155968, 2013). "Recent studies showed that IL-6 is important for promoting Th17 cell differentiation and orchestrating downstream pathways of Th17 immune responses to cause inflammatory and autoimmune disorders such as rheumatoid arthritis and multiple sclerosis." (PMID 24454477, 2013). "It stimulates a unique CD4+ inflammatory T-cell characterized by secretion of IL-17, tumor necrosis factor and IL-6, which are strongly associated with proinflammatory responses and severe autoimmunity." (PMID 23767933, 2013). "Since the underlying mechanisms of persistent IL-6 maintenance in autoimmunity remained so far elusive these observations uncover a potential explanation." (PMID 24155968, 2013). "In combination with transforming growth factor-β, IL-6 is also involved in differentiation of naïve CD4+ T cells into a pro-inflammatory T helper (Th) 17 phenotype that has been associated with autoimmunity." (PMID 22509338, 2012). "Early after infection, IL-6 acts to dampen the strength of initial anti-viral immune response to reduce the risk of developing autoimmunity, however, its long-term presence as a chronic participant leads to heightened chronic disease." (PMID 19587788, 2009). "For example, polymorphisms in genes such as IL-6 may influence both neurodegeneration and autoimmunity." (PMID 40937231, 2025). "Using GeneHarmony, we were able to identify TNF (alias TNF-α) and IL6 as important genes associated with all three disease groups, which might provide further insight into SjD development of autoimmunity systemically." (PMID 40650157, 2025). "While most patients with GFAP autoimmunity respond well to glucocorticosteroids, this treatment is associated with various side effects, and a subset of patients relapse; IL6 pathway blockade could be considered in this population." (PMID 39869499, 2025). "The hypothesis that IL-6 is implicated in autoimmunity was advanced while studying patients affected by cardiac myxoma." (PMID 38893662, 2024). "Since its discovery decades prior, interleukin 6 has proven to be functionally pleiotropic, and when dysregulated, to participate in a number of inflammatory cascades underlying pathophysiology of a range of autoimmune conditions." (PMID 37841263, 2023). "This IL-6 cluster signaling has been reported to be crucial for the development of pathogenic Th17 cells, and depletion of IL-6 or IL-6R only on DCs protected mice in an experimental autoimmune mouse model." (PMID 38469154, 2023). "In the early stages, IL-6 participates in vascular endothelial activation and apoptosis, leading to the release of damage-associated molecular patterns (DAMPs), which maintain inflammation and autoimmunity." (PMID 35203527, 2022). "B cell–intrinsic TLR7 signaling and IL-6 production promote the development of spontaneous germinal centers (GCs) in secondary lymphoid tissues, which are associated with autoinflammation and autoimmunity." (PMID 35653193, 2022). "CD40 is a member of the TNF receptor (TNFR) family, whose expression in macrophages has been associated with pathologic conditions, and IL-6 has been described as a crucial pleiotropic pro-inflammatory cytokine that regulates inflammation during cancer, autoimmunity, and infectious diseases." (PMID 35745755, 2022).
Autoimmunity (continued). "The extent to which their induction by IL-6 promotes autoimmunity by sustaining a pathogenic, pro-proliferative cell phenotype—indeed, whether their modulation might favour tolerance induction—warrants concerted investigation." (PMID 30753680, 2019). "The increase in IL6 signaling observed in T1D patients modulates immune response through the expansion of pathogenic Th17 cells and inhibition of generation of Foxp3 + T-regulatory cells is associated with T1D autoimmunity." (PMID 29445381, 2018). "The involvement of autoimmunity is considered to be mediated by innate antibodies, which cause the release of several cytokines, such as interleukin-6 (IL-6) and vascular endothelial growth factor (VEGF), thereby playing an important role in clinical flares of iMCD." (PMID 30293532, 2018). "However, persistent dysregulation of IL6 production (e.g., if senescent cells have accumulated in a given tissue) has been implicated in several autoimmune conditions, chronic inflammatory diseases, and cancer." (PMID 30086537, 2018). "IL-6 and other inflammatory cytokines may cause autoimmunity through systemic inflammation." (PMID 38107861, 2023). "Hence, our findings suggest that IL-6-induced STAT1 may promote early events that govern the transition into pathogenic T cells driving autoimmunity." (PMID 35911690, 2022). "IL-6 was linked with worsening disability in MS patients, while TNF-α was linked to a family history of autoimmunity." (PMID 41771986, 2026). "IL-6, a multifunctional cytokine, is recognized as a pivotal component of the immune system, bridging innate and adaptive immunity, as well as autoimmunity." (PMID 40471558, 2025). "IL‐6 is produced in response to infections and tissue injuries and plays different roles in different contexts, while dysregulated continual synthesis of IL‐6 has a pathological effect on chronic inflammation and autoimmunity." (PMID 40692664, 2025). "Although IL-6 is well known to be released in large amounts during infection, autoimmunity and cancer, it is also released by skeletal muscles during exercise." (PMID 41379843, 2025). "Concerning the pathophysiology of MOGAD, IL-6 is a pivotal driver in CNS inflammation and autoimmunity." (PMID 40717732, 2025). "The analysis of IL-6 is of interest given the known inflammatory effects of IL-6 in autoimmunity along with the relevance to IFN via STAT signalling pathways." (PMID 41050477, 2025). "IL-6 is a determinant for the development of autoimmunity and neuroinflammation, because it is involved in multiple sclerosis (MS) immunopathogenesis." (PMID 38928437, 2024). "The 2nd top biomarker, TNFSF14 (also known as LIGHT), promotes the differentiation of various inflammatory cells and IL-6 production, inhibits T cell activation, and reduces Th1 chemokine expression in other autoimmune disorders." (PMID 39165841, 2024). "Of note, it is known that progressive and uncontrolled levels of IL-6 production by follicular B-cells led to the development of chronic inflammation and multiorgan autoimmunity in aging p50−/− mice." (PMID 39337370, 2024). "IL-6 is a determinant for the development of autoimmunity and neuroinflammation and is involved in the pathogenesis of MS." (PMID 38928437, 2024). "Significant IL-6 production and B cell expression of IL-6R have been linked to SLE and a number of other autoimmune disorders." (PMID 38893662, 2024). "Nonetheless, our findings with IL-6 provide support for the partial uncoupling of drivers of antitumor immunity and irAE-related autoimmunity." (PMID 39403935, 2024). "While current therapeutic approaches involve IL-6-neutralizing antibodies to manage inflammation and autoimmunity, these treatments can be costly." (PMID 39867697, 2024). "Such dysregulated IL-6 expression in aflatoxicated animals is indicative of tissue damage and inflammatory reactions by aflatoxin metabolites as well as a predictive of autoimmunity." (PMID 37840065, 2023).